OLFM3 (olfactomedin 3)
Synonyms: NOE3; NOELIN3; OPTIMEDIN
Tractability: Antibody: UniProt places it where antibodies can reach, with medium confidence; UniProt predicts a signal peptide or a membrane-spanning region; its Gene Ontology location is reachable by antibodies, with medium confidence.
Gene: Protein-coding gene on chromosome 1 (101,802,560 to 101,997,020, reverse strand). Ensembl gene ENSG00000118733.
Subcellular location: Secreted; Synapse
Subcellular location (Human Protein Atlas): Vesicles; Predicted to be secreted
Gene Ontology:
Molecular function: protein binding
Biological process: signal transduction; eye photoreceptor cell development
Cellular component: AMPA glutamate receptor complex; extracellular region; Golgi apparatus; synapse
Genetic constraint (gnomAD): Loss-of-function variants: 20 observed, 49.33 expected, observed/expected ratio (o/e) 0.41, 90% interval 0.28 to 0.59. The upper end of that interval is the gene's LOEUF score, 0.59, which puts it in group 2 of 6, group 1 being the genes least tolerant of losing a copy. Missense variants: 437 observed, 572.15 expected, observed/expected ratio (o/e) 0.76, 90% interval 0.7 to 0.83. Synonymous variants: 222 observed, 210 expected, observed/expected ratio (o/e) 1.06, 90% interval 0.95 to 1.18.
Homologues: Orthologues: chimpanzee OLFM3 (96% identical), macaque OLFM3 (96% identical), dog OLFM3 (96% identical), guinea pig OLFM3 (96% identical), pig OLFM3 (96% identical), mouse Olfm3 (96% identical), rat Olfm3 (96% identical), rabbit OLFM3 (95% identical), tropical clawed frog olfm3 (84% identical), zebrafish olfm3a (83% identical), zebrafish olfm3b (79% identical). Paralogues in human: OLFM1 (63% identical), OLFM2 (60% identical), MYOC (26% identical), OLFML2B (26% identical), OLFML2A (25% identical), OLFM4 (23% identical), GLDN (20% identical), OLFML1 (19% identical), OLFML3 (18% identical).
Diseases named in the same sentence as OLFM3 in open-access papers:
OLFM3 is named in the same sentence as 10 diseases in open-access papers, as found by Europe PMC text mining. Sharing a sentence is not in itself a finding about the gene and the disease. The quoted sentences say what the papers report.
dementia (1 paper, 2025). Loss of intellectual abilities interfering with an individual's social and occupational functions. "SNP rs61804494 (G/A) around gene OLFM3 had significant interaction signals for all three dementia outcomes (all P < 0.009), and the protective association effects of FOS with the three outcomes increased linearly with each additional copy of G allele." (PMID 40949174, 2025).
epilepsy (1 paper, 2020). A brain disorder characterized by episodes of abnormally increased neuronal discharge resulting in transient episodes of sensory or motor neurological dysfunction, or psychic dysfunction. "In recent years, differences in the gene encoding OLFM3 have been found between patients with epilepsy and controls." (PMID 32850838, 2020). "Differences in the gene coding for OLFM3 have been found between patients with epilepsy and controls." (PMID 32850838, 2020). "Next, OLFM3 expression in mouse models of epilepsy induced by PTZ and KA was assessed by Western blotting." (PMID 32850838, 2020). "In the KA-induced epilepsy model, OLFM3-LV injection shortened the spontaneous seizure onset latency, while OLFM3-shRNA injection prolonged the onset latency compared with Con-sh injection." (PMID 32850838, 2020). "The expression of OLFM3 was significantly increased in the epileptic focus specimens of patients and in the hippocampus and cortex of the classic models of epilepsy." (PMID 32850838, 2020). "Follow-up experiments were performed to detect whether OLFM3 deletion might have beneficial effects on the two epilepsy models." (PMID 32850838, 2020). "Downregulation of OLFM3 may have a therapeutic effect on epilepsy." (PMID 32850838, 2020). "It is not known whether the increase of OLFM3 caused by epilepsy or epilepsy caused by the increase of OLFM3." (PMID 32850838, 2020). "Therefore, we investigated whether OLFM3 interacts with AMPARs and participates in the pathogenesis of epilepsy." (PMID 32850838, 2020). "In this paper, we found that OLFM3 expression was significantly increased in the brains of TLE patients and two classic models (PTZ- and KA-induced mouse models of epilepsy)." (PMID 32850838, 2020). "Whether OLFM3 also plays a certain regulatory role in the formation of AMPAR complex to participate in the development of epilepsy, unfortunately, there has been no relevant report before." (PMID 32850838, 2020). "However, the exact role of OLFM3 in epilepsy has not been thoroughly investigated." (PMID 32850838, 2020). "However, how OLFM3 participates in the formation of the AMPAR complex and whether it is involved in the occurrence of epilepsy have not been studied." (PMID 32850838, 2020).
multiple sclerosis (1 paper, 2014). A progressive autoimmune disorder affecting the central nervous system resulting in demyelination. "It is flanked by S1PR1 and OLFM3 genes, and is 200 kb from a multiple sclerosis susceptibility gene." (PMID 24511991, 2014).
myelofibrosis (1 paper, 2018). A partial or complete replacement of the bone marrow stroma by fibrous tissue. "Importantly, upregulation of CXCL12, ASPN, and OLFM3, factors secreted by CAF, has been observed; CXCL12, through the interaction with its receptor CXCR4, can lead to CXCL12 and TGFβ production and concur to myelofibrosis." (PMID 29515580, 2018).
neuroblastoma (1 paper, 2021). Neuroblastoma (NB) is the most common solid, extracranial childhood tumor. "miRNA appeared to be downregulated in neuroblastoma cell lines due to promoter methylation, but treatments with 5′azacitidine increased miRNA expression and led to malignancy decrease through downregulation of miRNAs’ targets such as CDK6, DNMT3B, E2F3, OLFM3, and IFNAR1." (PMID 34832966, 2021).
type 2 diabetes (1 paper, 2025). "OLFM3 has been found to be expressed in amyloid plaques from AD patients and RUXF was classified among the top 10 hub shared between AD and type 2 diabetes." (PMID 39891246, 2025).
OLFM3 also shares sentences with these, for which no sentence is quoted: bladder cancer (1 paper); Epileptic Seizure (1); temporal lobe epilepsy (1); tumor (1).